CLCN1 (chloride voltage-gated channel 1)
Diseases named in the same sentence as CLCN1 in open-access papers (continued):
Sharing a sentence is not in itself a finding about the gene and the disease.
cardiac arrhythmia (4 papers, 2020 to 2022). Any disturbances of the normal rhythmic beating of the heart or MYOCARDIAL CONTRACTION. "Since no extra-muscular and especially cardiac manifestations of NDM are reported in other NDM-CLCN1 cohorts so far and given the low number of patients with cardiac arrhythmias in our cohort, a causal relation between CLCN1 mutation and cardiac manifestations stays unlikely." (PMID 33263785, 2021). "Additionally, deep RNA sequencing identified 17 downregulated genes and 5 upregulated genes in DOX+ mice, among which Ppp1r13l, Clcn1, and Agt have previously been linked to arrhythmias." (PMID 32260593, 2020). "Interestingly, three of these genes, Ppp1r13l, Clcn1 and Agt have been previously linked to cardiac arrhythmias." (PMID 32260593, 2020).
Myalgia (3 papers, 2015 to 2021). "These CLCN1 mutations were found in seven patients who exhibited typical myotonic symptoms such as muscle stiffness that disappeared upon muscle activity (warm-up phenomenon), muscle hypertrophy and myalgias in some of the cases and typical myotonic bursts in EMG recordings." (PMID 26502825, 2015).
congenital myopathy (2 papers, 2017 to 2025). "Notably, three muscle-specific genes, ACTA1, TPM3, and CLCN1, were associated with hereditary skeletal myopathy and congenital myopathy." (PMID 41297061, 2025).
Dystonia (2 papers, 2015 to 2025). An abnormally increased muscular tone that causes fixed abnormal postures. "Additional research is required to elucidate the functional implications of CLCN1 mutations and their potential involvement in neurological conditions, particularly dystonia and other movement disorders." (PMID 40223930, 2025).
leukodystrophy (2 papers, 2017 to 2021). Leukodystrophies are a group of rare, progressive, metabolic, genetic diseases that affect the brain, spinal cord and often the peripheral nerves. "As proof of concept, we present novel mouse models for multiple known human diseases representing different developmental etiologies, including segmentation defects (Hes7), leukodystrophy (Galc) and neuromuscular disease (Clcn1 and Large1)." (PMID 34142127, 2021).
Ataxia (1 paper, 2020). Ataxia refers to impaired coordination of voluntary muscle movement. "The effect of a CLCN1 frameshift in the acetazolamide-responsive patient (Case-14) with severe ataxia, nausea, vomiting, and nystagmus at the age of 27, raised the possibility of phenotypic variability within the same genotype p.Gly945ArgfsX39 mutation." (PMID 32466254, 2020).
distal hereditary motor neuronopathy (1 paper, 2015). "Several deleted genes have also been implicated in autosomal dominant movement disorders including CLCN1 (Thomson dominant myotonia) and DHMN1 (distal hereditary motor neuronopathy)." (PMID 26064708, 2015).
Epileptic encephalopathy (1 paper, 2015). A condition in which epileptiform abnormalities are believed to contribute to the progressive disturbance in cerebral function. "Furthermore, variations in CLCN1, CLCN2, and CLCN4 have been reported in patients with idiopathic epilepsy and epileptic encephalopathy; however, the association of some variants with disease pathogenesis is still controversial." (PMID 25794116, 2015).
generalized epilepsy (1 paper, 2015). Epilepsy that is characterized by generalized seizure types and may have typical interictal and/or ictal EEG findings that accompany generalized seizure types (for example generalized spike-wave). "A recent de novo CLCN1 truncation mutation in a patient with generalized epilepsy indeed postulates an unexpected role of this channel in the control of neuronal network excitability." (PMID 25964741, 2015).
hyperlipidemia (1 paper, 2023). "Although the gene Clcn1 selected via MR was certificated in the enrichment pathways from mice liver RNA-seq data, it seemed to have a minimal association with hyperlipidemia." (PMID 37888673, 2023).
myotonic dystrophy type 2 (1 paper, 2015). Myotonic dystrophy type 2 (MD2), also known as proximal myotonic myopathy, is a very rare genetic multi-system disorder of late childhood or adult-onset characterized by mild myotonia, muscle weakness, and rarely cardiac conduction disorders. "These aberrant-splicing, which may also occur in myotonic dystrophy type 2 (DM2) patients, leads to premature termination codons, with a consistent decrease of the mRNA of CLCN1, of ClC-1 protein and consequently of gCl." (PMID 26208967, 2015).
Oropharyngeal dysphagia (1 paper, 2024). "Oropharyngeal dysphagia was described in the Labrador retriever, recently reported with a CLCN1 variant." (PMID 38473107, 2024).
ptosis (1 paper, 2021). The drooping of the upper eyelid. "His only manifestation at the time of blood sampling was unilateral ptosis while both this son and the mother of the proband were found to be heterozygous carriers of the p.Arg894* CLCN1 variant." (PMID 34501382, 2021).
skin cutaneous melanoma (1 paper, 2015). "Surprisingly, four of the genes containing RRA missense mutaions in Uveal Melanoma (DCC, CR1, GCC2 and CLCN1) were predicted as diver genes in TCGA skin cutaneous melanoma dataset." (PMID 25903059, 2015).
myopathy (10 papers, 2016 to 2025). A disease of the muscle in which the muscle fibers do not function properly. "Consistent with this is the observation that the muscle biopsy from patients and rats treated with fluvastatin exhibit manifestations of myopathy in which the skeletal muscles show lowered ClC-1 protein expression and decreased chloride conductance with no change in ClCN1 transcript levels." (PMID 36428957, 2022). "Using ASO to specifically target the 3′ splice site of CLCN1 exon 7a, or the more general CUG repeat region of DMPK1, improves myopathy in DM1 mouse models." (PMID 35165120, 2022). "Furthermore, it is likely that in combination with the splicing defects in other muscle genes involved in calcium handling (Serca1) and excitability (Clcn1), the mitochondrial damage observed in the CaV1.1ΔE29/ΔE29 mice might be aggravated, and thus contribute to the myopathy." (PMID 26965373, 2016).
neuromuscular disease (5 papers, 2018 to 2023). "Non-dystrophic myotonias (NDM) are rare hereditary neuromuscular diseases caused predominantly by mutations in CLCN1 or SCN4A, respectively coding for the voltage-gated muscle channels ClC-1 and NaV1.4." (PMID 33263785, 2021).
skeletal muscle disorder (4 papers, 2016 to 2025). A disease involving the skeletal muscle tissue. "For example, Becker-type myotonic dystrophy is a skeletal muscle disorder caused by recessive mutations in the CLCN1 gene, which encodes the chloride voltage-gated channel 1 protein." (PMID 34142127, 2021).
tumor (2 papers, 2019 to 2025). "This shows that CLCN1 may serve as a tumor suppressor gene in OSCC which may be because chloride channels are involved in the regulation of cell cycle." (PMID 31396442, 2019).
neurological disorders (1 paper, 2025). "Notably, the presence of polymorphic alleles in the CLCN1 gene among patients with idiopathic epilepsy indicates the potential involvement of ClC-1 chloride channels in neurological disorders." (PMID 40223930, 2025).
CLCN1 also shares sentences with these, for which no sentence is quoted: channelopathy (8 papers); infection (4); Bartter syndrome (3); cancer (3); fungal infection (3); genetic disease (3); muscle disorder (3); congenital myasthenic syndrome (2); Dent disease (2); muscular dystrophy (2); myotonic disorders (2); osteopetrosis (2); periodic paralysis (2); angiosarcoma (1); Apnea (1); Arrhythmia (1); Atrophy (1); breast carcinoma (1); Brugada syndrome (1); congenital muscular dystrophy (1); dementia (1); diabetes (1); distal myopathy (1); Duchenne muscular dystrophy (1); glycogen storage disease (1); heart failure (1); hereditary muscle disorder (1); hyperkalemic periodic paralysis (1); hypokalemic periodic paralysis, type 2 (1); Infertility (1).
A further 20 diseases each share a sentence with CLCN1 in 1 paper.